ADGRF5P1 (adhesion G protein-coupled receptor F5 pseudogene 1)
Synonyms: GPR116P1
Gene: Transcribed processed pseudogene on chromosome 9 (62,860,873 to 62,862,007, reverse strand). Ensembl gene ENSG00000227582.
Diseases named in the same sentence as ADGRF5P1 in open-access papers:
ADGRF5P1 is named in the same sentence as 1 disease in open-access papers, as found by Europe PMC text mining. Sharing a sentence is not in itself a finding about the gene and the disease.
ADGRF5P1 shares sentences with these, for which no sentence is quoted: glioma (1 paper).